CHAT (choline O-acetyltransferase)
Diseases named in the same sentence as CHAT in open-access papers (continued):
Sharing a sentence is not in itself a finding about the gene and the disease.
Hydrocephalus (1 paper, 2023). Hydrocephalus is an active distension of the ventricular system of the brain resulting from inadequate passage of CSF from its point of production within the cerebral ventricles to its point of absorption into the systemic circulation. "In line with the co-localization of the majority of these 24 functional-anatomic cell groupings with ChAT, a key enzyme in the biosynthesis pathway of the neurotransmitter acetylcholine, the cholinergic system has also been associated with hydrocephalus in several prior studies." (PMID 36707519, 2023).
hypothyroidism (1 paper, 2015). Abnormally low levels of thyroid hormone. "Indeed, this hypothesis is consistent with studies that have reported decreased choline acetyltransferase (ChAT; involved in the synthesis of ACh) activity and protein concentration in hypothyroidism." (PMID 25371181, 2015).
intestinal inflammation (1 paper, 2017). "Enteric neuropathy in intestinal inflammation may be influenced by excessive nitric oxide, while inflammation-associated loss of ChAT-IR neurons has been associated with decreases in the number of myenteric neurons." (PMID 28420434, 2017).
intestinal motility disorders (1 paper, 2013). "Neuronal nitric oxide synthase (nNOS)-producing neurons and choline acetyl transferase (chAT)-producing neurons are involved in the regulation of intestinal motility, and nNOS/chAT misbalance has been reported in certain intestinal motility disorders." (PMID 24423414, 2013).
lung adenocarcinoma (1 paper, 2025). A carcinoma that arises from the lung and is characterized by the presence of malignant glandular epithelial cells. "For comparison, we also examined ChAT expression in two SCLC neuroendocrine cell lines (H82 and H69) and one NSCLC lung adenocarcinoma cell line (A549)." (PMID 41226363, 2025).
lymphoma (1 paper, 2023). A malignant (clonal) proliferation of B- lymphocytes or T- lymphocytes which involves the lymph nodes, bone marrow and/or extranodal sites. "High expression of the surface protein CD36, the transcription factors Early Growth Response Protein 1, Cyclin D1, and L-Myc and of the enzyme ChAT have been linked to tumor progression, poor survival and increased metastasis in several cancers, including melanoma and recently also in lymphoma." (PMID 36831273, 2023). "High CHAT overexpression (≥100-fold), as shown in L-1236, may result in non-neuronal production and release of acetylcholine by Hodgkin and Reed–Sternberg cells, thereby self-promoting lymphoma growth." (PMID 36831273, 2023).
morbid obesity (1 paper, 2024). An excess of body weight, normally defined as an individual with a body mass index greater than 35 or a body weight greater than one hundred percent of ideal body weight. "Since in morbid obesity WAT is infiltrated by circulating macrophages that display an M1-polarized proinflammatory phenotype, we evaluated the percentage of ChAT-positive cells also expressing the CD11c M1 proinflammatory macrophage marker or the CD206 M2 anti-inflammatory macrophage marker." (PMID 38141849, 2024).
Motor neuron atrophy (1 paper, 2019). Wasting involving the motor neuron. "RG108 suppressed spinal motor neuron atrophy in AR‐97Q mice, and ChAT protein levels were elevated in the spinal cords of RG108‐treated SBMA mice compared with their DMSO‐treated counterparts." (PMID 30940675, 2019).
mucoepidermoid carcinoma (1 paper, 2015). A carcinoma morphologically characterized the presence of cuboidal mucous cells, goblet-like mucous cells, squamoid cells, cystic changes, and a fibrotic stromal formation. "The only case with high expression of ChAT was identified to be mucoepidermoid carcinoma." (PMID 25591716, 2015).
non-alcoholic steatohepatitis (1 paper, 2023). "To further substantiate the role of ChAT-expressing T cells in liver tumorigenesis, we used an alternative disease model in which Chatfl/fl; Cd4-cre and Chatfl/fl mice were fed long term on a Western diet (high fat, high cholesterol and high sugar) to induce non-alcoholic steatohepatitis (NASH)." (PMID 37640929, 2023).
non-small cell lung carcinoma (1 paper, 2023). A group of at least three distinct histological types of lung cancer, including non-small cell squamous cell carcinoma, adenocarcinoma, and large cell carcinoma. "For instance, ChAT is upregulated in non-small cell lung carcinoma (NSCLC), while cholinesterase enzymes are downregulated, leading to increased ACh in cancer tissues." (PMID 37828429, 2023).
ovarian carcinoma (1 paper, 2012). A malignant neoplasm originating from the surface ovarian epithelium. "Many studies have demonstrated that ACh and other components of cholinergic signaling, including ChAT, cholinesterase, M and N cholinergic receptors, are present in a variety of non-neuronal tissues, including most common cancer cells such as NSCLC, SCLC, colon, glial, breast and ovarian carcinomas." (PMID 23285263, 2012).
periodontal disease (1 paper, 2022). "The cholinergic system, including ACh, choline acetyltransferase (ChAT), acetylcholinesterase (AChE), and nicotinic or muscarinic acetylcholine receptors (AChRs), is involved in periodontal disease." (PMID 36430624, 2022).
peritonitis (1 paper, 2024). Inflammation of the peritoneum (tissue that lines the abdominal wall and covers most of the organs in the abdomen). "Here, we identify a significant population of macrophages (Mφs) expressing ChAT and synthesizing acetylcholine in the resolution phase of acute peritonitis." (PMID 38923993, 2024). "To further evaluate the expression of ChAT in Mφs during bacterial infection, we adopted a self-resolving model of peritonitis induced by Escherichia coli or Staphylococcus aureus." (PMID 38923993, 2024). "Our study addresses this gap by revealing a notable proportion of peritoneal Mφs expressing ChAT in the resolution phase of TLR ligands-induced peritonitis and bacterial infections." (PMID 38923993, 2024). "The expression of ChAT Mφs was significantly increased at the resolution phase (72 h) but not at the acute phase of either E. coli-induced peritonitis (4 h) or S. aureus-induced peritonitis (24 h)." (PMID 38923993, 2024).
prion disease (1 paper, 2015). A transmissible disease that is caused by a protein that is able to induce abnormal folding of normal cellular proteins, leading to characteristic spongiform brain changes, which are associated with neuronal loss without an inflammatory response. "Conversely, the cholinergic ChAT mRNA levels were not significantly different, suggesting that prion disease affects AChE in a specific manner." (PMID 25853328, 2015).
prostate carcinoma (1 paper, 2019). A carcinoma that arises from epithelial cells of the prostate gland. "It was shown that in the prostate epithelium, CHAT participates in autocrine cholinergic signaling potentially involved in prostate cancer invasion and metastasis." (PMID 31447885, 2019).
R6 (1 paper, 2021). "In contrast, CHAT expression was decreased in YAC72 and R6/1 HD mouse brains." (PMID 34215255, 2021).
renal hypertension (1 paper, 2022). Hypertension caused by the kidney's hormonal response to narrowing or occlusion of the renal arteries. "Our results indicated that renal hypertension in rats decreased the expression of ChAT in the hippocampus, an effect that was reversed by the treatment with captopril but not with losartan." (PMID 35528844, 2022).
squamous cell carcinoma (1 paper, 2015). A carcinoma arising from squamous epithelial cells. "A total of three of the 18 lung tumors (one squamous cell carcinoma, one adenocarcinoma and one atypical carcinoid) did not exhibit expression of ChAT and ChoK, which were assigned to group 1." (PMID 25591716, 2015).
squamous cell lung carcinoma (1 paper, 2023). A carcinoma arising from squamous bronchial epithelial cells. "Similarly, ChAT was significantly upregulated in squamous cell lung carcinoma compared to adjacent healthy specimens." (PMID 37828429, 2023).
T-cell deficiency (1 paper, 2019). "Although NOS2 expression is characteristically elicited by IFNγ-induced activation of STAT1-dependent gene transcription, expression of this cytokine was not affected by ChAT T-cell deficiency." (PMID 30973939, 2019).
Yoon-Bellen neurodevelopmental syndrome (1 paper, 2023). "In proband BR1, the heterozygous deletion did not contain dominant disease genes, but three recessive genes (SLC38A1, CHAT and OGDHL) with a muscle phenotype: congenital myasthenic syndrome type 21 or type 6, or Yoon-Bellen neurodevelopmental syndrome, respectively." (PMID 36781956, 2023).
infection (18 papers, 2014 to 2025). The state of being infected such as from the introduction of a foreign agent such as serum, vaccine, antigenic substance or organism. "ChAT transcript levels as well as numbers of ChAT-expressing cells in the gut epithelium remained unaffected by pathogenic infection." (PMID 38063293, 2023). "ChatBKO mice showed 10-fold reductions in lung viral loads at 1 dpi with influenza A/PR8 compared to mb-1Cre−/− ChATfl/fl control mice (Control), consistent with relatively high constitutive expression of ChAT by B cells prior to infection." (PMID 38978583, 2024). "Twenty‐one days after infection, ChAT‐positive cells transgenically expressing mCherry‐tagged hM3D (Gq) were detected in DMV of mice." (PMID 36050877, 2022). "To calculate infection yield of motor neurons, we measured the number tdTomato-expressing neurons co-labelled with ChAT within the ipsi- or contralateral spinal cord tissue sections sampled (n = 13 animals; 10 sections/animal)." (PMID 33837249, 2021). "T cells express both muscarinic and nicotinic acetylcholine (ACh) receptors and expression of the enzyme choline acetyltransferase (ChAT) is induced in T cells during infection, T cell derived ACh is involved in T cells migration to tissues." (PMID 34593857, 2021). "Here we demonstrate that infection with C. rodentium induces ChAT+ T-cell recruitment and that expression of ChAT by this T-cell population significantly augments host defenses." (PMID 30973939, 2019). "While significantly increased production of pyruvic acid was detected in the feces from uninfected ChAT T-cell cKO mice, infection reduced the concentration of this metabolite to levels observed in uninfected or C. rodentium infected control mice." (PMID 30973939, 2019). "Our analysis indicates that Cxcl13 but not Ccl8 expression is induced beginning 10 days p.i. until day 30 p.i., a period during infection that closely mirrors when the number of ChAT+ T-cells increased in the colon." (PMID 30973939, 2019). "Despite the increased expression of pro-inflammatory cytokines during C. rodentium infection, inducible nitric oxide synthase (Nos2) expression was significantly reduced in intestinal epithelial cells of ChAT T-cell cKO mice 10 days post-infection." (PMID 30973939, 2019). "In samples from mice at early onset of paralysis, EV-D68 ir was co-localized with ChAT ir, indicating direct infection of motor neurons by the virus, which probably led to the death and depletions of motor neurons during the five-week period of paralysis." (PMID 29329211, 2018). "We thus re-examined the MoXII in ChAT-immunostained sections after ΔG-RV infection of the left masseter muscle." (PMID 24843003, 2014). "Lung tissue ChAT + B cells are shown to interact with a7 nicotinic Ach receptor-expressing lung interstitial macrophages in mice within 24h of infection to control their production of TNFa, shifting the balance towards reduced inflammation at the cost of enhanced viral replication." (PMID 38978583, 2024). "Interestingly, during NF45-infection, we notice the upregulation of DEG encoding for spinal motor neuron-specific marker choline acetyltransferase (ChAT), the enzyme responsible for the biosynthesis of neurotransmitter acetylcholine." (PMID 39735262, 2024). "B cells remained the predominant population of ChAT-GFP + cells at early infection timepoints." (PMID 38978583, 2024). "Increased expression of neuromotor-related genes such as Adam22, Cacnb4 and Zic1 (activated by NF1_LV infection) and ChAt (activated by NF45_LV infection) could explain PAM symptoms such as muscle weakness and seizures." (PMID 39735262, 2024). "The increased production of the inhibitory neurotransmitter NO occurs with concomitant reduction in the expression of ChAT at 1 week of infection when the nerve-mediated contractions and nerve coordinated gastrointestinal motility significantly differ from sham infected mice." (PMID 29600197, 2018).
infection (continued). "Moreover, all ChAT-expressing T cells had an activated CD44hi CD62Llo phenotype, a cell population that does not appear in the lungs of infected mice until around day 5–7 of infection." (PMID 38978583, 2024). "Recent work describes that this relay is at play in the intestine: ChAT+ T cells are recruited to the colon during C. rodentium infection, and T cell-specific ChAT deficiency renders mice more susceptible to infection, suggesting a nonredundant role of T cell-derived ACh in host defense." (PMID 33542493, 2021). "B cells are the most prevalent ACh-producing leukocyte population in the respiratory tract demonstrated with choline acetyltransferase (ChAT)-green fluorescent protein (GFP) reporter mice, both before and after infection with influenza A virus." (PMID 40263611, 2025). "Here, infection with O. ostertagi induced the expression of some Tuft cell markers, including POU2F3, CHAT, TRPM5, and GFI1B in cattle." (PMID 40076885, 2025). "Our results regarding the infection of CK18- and ChAT-positive cells can explain the dysfunction of the MOE microenvironment." (PMID 34452517, 2021). "In the striatum, the immunostaining data showed that the ratio of enhanced green fluorescent protein (EGFP)+-ChAT+ cells/ChAT+ cells was 88.94% ± 3.19%, and the ratio of EGFP+-ChAT+ cells/EGFP+ cells was 82.75% ± 2.42%, which indicated high infection efficiency." (PMID 37223477, 2023). "Confocal microscopy on colonic tissue sections and flow cytometry experiments confirmed NOS2 expression was significantly increased in colonic IEC of WT mice, but not in ChAT T-cell cKO mice during infection." (PMID 30973939, 2019). "Thus, innate signal-induced ChAT+ B but not ChAT+ T cells rapidly respond to affect influenza A virus replication in the lung within the first 24 h of infection." (PMID 40263611, 2025). "While leukocyte-derived ACh effects in the spleen have been shown previously to require T cell-mediated ACh production, T cell-specific deletion of ChAT (Chatfl/fl- LckCre+/−) did not affect influenza virus loads at 1 dpi, consistent with their low frequencies in all tissues prior to infection." (PMID 38978583, 2024). "ChAT-GFP+ IL-22+ T-cell population appears to be persistent in the naïve colon and does not increase significantly during infection." (PMID 30973939, 2019).
neurodegenerative disease (16 papers, 2012 to 2025). A disorder of the central nervous system characterized by gradual and progressive loss of neural tissue and neurologic function. "In the development of most neurodegenerative diseases, ChAT expression is typically decreased, particularly in the conditions and CNS regions with significant cholinergic neurons’ loss." (PMID 39857801, 2025). "This transgenic mouse model will also be a useful tool to study the physiological function of the primate-specific 82-kDa ChAT and its role in cholinergic neuron vulnerability in physiological aging and neurodegenerative diseases." (PMID 36810877, 2023). "ChAT activity has been found to be reduced in neurodegenerative disease disease." (PMID 28521305, 2017). "Therefore, ChAT can be a potential target or neurodegenerative diseases prevention and therapy." (PMID 30410227, 2018). "Before the discovery of Trofinetide, GPE demonstrated modulatory effects on neurons and certain CNS enzymes (ChAT, GAD, NOS, and tyrosine hydroxylase) and was claimed to treat neurodegenerative diseases." (PMID 37568516, 2023). "In contrast, as predicted for a progressive degenerative disease, 13–14 month old APPL/S mice had ChAT neurites with reduced length and area compared to those in 9–11 month old APPL/S mice." (PMID 25153701, 2014). "Synaptic cholinergic dysfunction is a common feature of different neurodegenerative diseases, including ALS, but little is known regarding the possible relationship between ChAT abnormalities and the pathogenesis of MN degeneration." (PMID 23531559, 2013). "In neurodegenerative diseases (e.g., AD and ALS), selective degeneration occurs in central cholinergic neurons, spinal and peripheral cholinergic motor neurons, and parasympathetic cranial nerves, accompanied by a marked reduction in ChAT expression." (PMID 41226363, 2025).